CA9 (carbonic anhydrase 9)
Diseases named in the same sentence as CA9 in open-access papers (continued):
Sharing a sentence is not in itself a finding about the gene and the disease.
tumor (continued). "Here, we aimed to investigate the CA9 expression in serum and tumor from different stages of CRC patients and utilize sulfonamide derivative with indium-111 labeling as a probe for CRC nuclear imaging detection in vivo." (PMID 26447758, 2015). "It was found that the inhibition of tumor microcirculation by bortezomib was synchronized with its inhibitory effect on hypoxia response (as assessed by decreased expression of eGFP and CA9)." (PMID 26416246, 2015). "CA9 is a transmembrane protein which is found overexpressed in numerous tumor types and induced under hypoxic conditions." (PMID 24927770, 2014). "CA9 is an attractive target for anticancer therapy, because it is selectively expressed by tumor cells and shows highly restricted expression in normal tissue." (PMID 25376898, 2014). "Treatment of hypoxic, metastatic 4 T1 mouse breast tumors with a fluorescent sulfonamide CA9 inhibitor resulted in a significant inhibition of tumor growth." (PMID 25376898, 2014). "Treatment of HT-29 xenografts with the high affinity inhibitor of CA9 indanesulfonamide reduced tumor growth, and further regression was observed when the inhibitor was used in combination with radiotherapy." (PMID 25376898, 2014). "Univariate analysis revealed that CA9 expression in CNB specimens, CA9 expression in resected tissues, tumor size, lymph node status, and pathological response were significantly associated with DFS." (PMID 24893880, 2014). "Expression of these enzymes was statistically correlated with expression of glycolysis-associated enzymes such as Glut-1, CA9, and MCT-4, supporting the possibility of serine/glycine metabolism occurring in the tumor stroma." (PMID 24979213, 2014). "Pharmacologic interference of CA9 catalytic activity using monoclonal antibodies or CA9 specific small molecule inhibitors has been shown recently to impair primary tumor growth and metastasis." (PMID 25376898, 2014). "CA9 helps to keep a normal pH in tumor cells in a hypoxic microenvironment and allow tumor cell proliferation." (PMID 24349364, 2013). "CA9 reflects significant changes in tumor biology and decreased CA9 concentration is independently associated with poor survival in advanced renal cell carcinoma." (PMID 24349364, 2013). "SPIA in nine independent clinical studies of several tumor types with at least 2.0-fold up-regulated transcription of CA9 revealed the FA pathway as one of the most consistently activated pathways in these tumors." (PMID 24101905, 2013). "Hypoxia inducible factor-1 alpha (HIF-1α), induced by tumor hypoxia, regulates tumor cell metabolism and metastasis by up-regulation of c-Met, carbonic anhydrase 9 (CA9) and glucose transporter 1 (GLUT1)." (PMID 23927384, 2013). "The expression of CA9 is highly induced in various cancers under hypoxic conditions, which is functionally important for the growth and survival of tumor cells." (PMID 22748168, 2012). "EF5 had a moderate correlation with CA-9 expression in the xenografts (r = 0.51 in tumor and r = 0.52 in stroma), but the correlation between CA-9 and HP5 in the patients was poor." (PMID 24213469, 2012). "The lack of increased angiogenesis as reflected by CD31 count and tumor hypoxia as reflected by CA9 expression, in the setting of treatment failure of cediranib, was contrasted by a statistically significant increase in p-STAT3 expressing macrophages." (PMID 23013619, 2012). "Compared to control and cediranib-treated tumors, AZD1480 significantly reduced tumor hypoxia by 71 and 66%, respectively as assessed by CA9 staining (P<0.01)." (PMID 23013619, 2012). "Acidosis of the tumor microenvironment is common in hypoxic tumors which results in the induction of CA9." (PMID 21455298, 2011). "Up-regulation of CXCR4 in Treg correlated with the basal-like phenotype (P = 0.029) and tumour hypoxia, as indicated by CA9 expression (P = 0.049)." (PMID 21521526, 2011).
tumor (continued). "In a RCC model, RENCA tumours expressing CA9 were treated with tumour vaccine (hsp110+CA9) and temsirolimus." (PMID 21285988, 2011). "Using CA9 as a surrogate marker of hypoxia, in keeping with our previous studies, grade 3 basal-like tumours were more likely to be hypoxic (8/10 positive for CA9), compared to grade 3 luminal cancers (0/11 positive for CA9) (P < 0.001)." (PMID 21521526, 2011). "LDH transcript levels were also elevated in hypoxic tissue fragments but in the murine tumor model the spatial link was significantly weaker than for CA9 and GLUT1." (PMID 21306648, 2011). "Cancer vaccines were recombinant tumour-specific proteins (CA9 or gp100), and recombinant heat shock protein (HSP; hsp110) served as the immune adjuvant." (PMID 21285988, 2011). "In this study, necrotic lesions were detected in hypoxic areas of OCUM-12 tumours but were rarely found in OCUM-12/Hypo tumours, whereas pimonidazole, CA9, and HIF-1α staining revealed both areas to be hypoxic." (PMID 20145613, 2010). "Based on these features, CA9 is not only a tumour marker but also appears to be directly involved in the oncogenesis of different types of tumours." (PMID 20145613, 2010). "Although the degree of the cellular response to these stresses (such as CA9) can reflect the levels of stresses (low tumor pO2) and serve as “endogenous markers” of such stresses in human cancers, such connection are not absolute and direct." (PMID 20844768, 2010). "Overexpression of CA12 is also observed in von Hippel-Lindau(VHL)-defective tumor cells with CA9, and is believed to contribute in an acid extracellular PH in malignant tumors." (PMID 21040567, 2010). "CA9 was initially identified in HeLa cells; its expression has been found in a variety of tumor types including colorectal cancer." (PMID 19619339, 2009). "To confirm CA9 mRNA expression, we analysed 35 clinical samples, including normal and tumour tissue." (PMID 18841153, 2008). "We studied the expression of CA9 mRNA in both normal and tumour tissues from 35 patients, using real-time RT–PCR." (PMID 18841153, 2008). "The survival rate of patients with tumours showing low CA9 expression was significantly higher than that of patients with tumours showing high CA9 expression (P=0.0003)." (PMID 18841153, 2008). "Relatively low, but steady expression of AS is of considerable importance for clinical studies using CA9 transcription as a marker of hypoxic tumours for potential prognostic or predictive purposes." (PMID 18026188, 2008). "Because the AS variant can be present in the normoxic cells with normal phenotype in the absence of FL CA IX, it can produce false-positive results in the studies designed to assess hypoxia- and tumour-related expression of CA9 gene with prognostic intent." (PMID 18026188, 2008). "In this group of paired samples, CA9 mRNA expression levels were significantly higher in tumour tissues (0.022±0.038) (mean±s.d)." (PMID 18841153, 2008). "In cancer cells, CA9 staining was seen mainly in the plasma membrane, and at the border of tumours only the cancerous lesion showed positive staining." (PMID 18841153, 2008). "CA9 expression was correlated with tumour size (P=0.0235), tumour depth (P<0.0001), regional lymph node metastasis (P=0.0031), distant lymph node metastasis (P=0.0077), stage (P<0.0001) and blood vessel invasion (P=0.006)." (PMID 18841153, 2008). "In primary tumours, CA9 and Hif-1α expression were correlated with DEC-1 expression (P=0.05), presence of a fibrotic focus (P<0.007) and mixed/expansive growth pattern (P<0.001)." (PMID 16251878, 2005). "In most tumours, CA9 is a transmembrane enzyme with an extracellular active site, linked to aggressive tumour behaviour." (PMID 15558070, 2005).
tumor (continued). "Fibroblasts were positive in only one case, in the tumoral stroma adjacent to a fibrotic area, in a case containing membranous CA9+ tumour cell areas." (PMID 15558070, 2005). "CA9 expression was cytoplasmic (of weak or moderate intensity) in nine tumours or membranous (of moderate or strong intensity) in 12 tumours." (PMID 15558070, 2005). "Membranous expression of CA9 was significantly higher in large tumours, in tumours with the presence of a fibrotic focus, a high mitotic count or proliferation index, liver metastases, low MVD and shorter survival (P=0.0004)." (PMID 15558070, 2005). "CA9 expression is consistent with the upregulation of HIF-1α nuclear expression in poorly differentiated tumours, recalling the situation observed in most carcinomas studied so far." (PMID 15558070, 2005). "Expressions of CA9 and Hif-1α were correlated in primary tumours (P<0.001) and in lymph node metastases (P=0.005)." (PMID 16251878, 2005). "Primary tumours and lymph node metastases with CA9 or Hif-1α expression had a higher ECP% and TCP% (P<0.003); in primary tumours, mixed/expansive growth pattern and fibrotic focus were characterised by higher ECP% (P=0.03)." (PMID 16251878, 2005). "We correlated array mRNA fold changes with carbonic anhydrase 9 (CA IX) staining of tumours as a surrogate marker of hypoxia." (PMID 16052224, 2005). "Tumour HIF-1α nuclear expression was significantly correlated with that of CA9 membranous expression and low MVD." (PMID 15558070, 2005). "Carbonic anhydrase 9 expression at the tumour–liver parenchyma interface was present in only 12% of the BC liver metastases with a replacement growth, in contrast to all BC liver metastases with a non-replacement growth (P=0.02)." (PMID 15054467, 2004). "There was CA9 expression at the tumour–liver interface in only 16% of the BC liver metastases vs 54% of the CRC metastases (P=0.002)." (PMID 15054467, 2004). "Increased activity of LDH, being linked with intratumoral hypoxia and acidity, should be related with aggressive tumour features as shown in a previous study on CA9 in NSCLC." (PMID 12942121, 2003). "It seems that LDH, CA9 and HIFαs immunohistochemistry can reliably predict tumour aggressiveness related to acidity and hypoxia, although this requires further investigation." (PMID 12942121, 2003). "Recently, we identified the tumour-associated carbonic anhydrases (CA), CA9 and CA12 as hypoxia-inducible in tumour cell lines." (PMID 12671706, 2003). "CA9 is induced strongly by hypoxia in a number of tumour cell lines and the CA9 gene has a HIF-1 hypoxia response element (HRE) immediately 5′ to its transcriptional start site." (PMID 11953885, 2002). "Furthermore, to evaluate the role of the dysadherin/CA9 axis in tumor immune evasion, we assessed T-cell responses in a coculture system using CM from HCT116 cells." (PMID 41535258, 2026). "Furthermore, immunofluorescence (IF) analysis revealed that compared with control (ApcMin/+) mice, dysadherin-KO (Fxyd5−/−) mice presented lower CA9 expression in primary tumor lesions." (PMID 41535258, 2026). "Many therapies regulating tumor pH utilize small compounds or nanoparticles to suppress pH regulators like CA9, NHE1, among others, amplifying the effectiveness of various treatments including chemotherapy, radiotherapy, photodynamic therapy (PDT), and chemodynamic therapy (CDT)." (PMID 40873634, 2025). "The hypoxic response could serve as a prognostic marker and therapeutic target for instance, via imaging with hypoxia tracers or by immunohistochemistry for CA9/HIF-1α in tumor biopsies." (PMID 41174561, 2025). "Immunologically, tumor cells are positive for CA9 and CK7, and ELOC shows nuclear positivity." (PMID 41306531, 2025).
tumor (continued). "The cell type-specific markers we used for cell annotation were as follows: T cell (CD3D); NK cell (KLRD1 and NKG7); plasma cell (IGKC and JCHAIN); Mast cell (KIT and TPSB2); tumour cell (CA9, NDUFA4L2 and SLC17A3); endothelium (PECAM1, PTPRB and KDR); mesangial cell (ACTA2 and PDGFRB)." (PMID 40830065, 2025). "Our data provide mechanistic support for this correlation: the hypoxia-induced upregulation of CA9 and other effectors likely enhances tumor cell survival under stress, facilitates extracellular matrix degradation, and supports early steps in the metastatic cascade." (PMID 41174561, 2025). "Interestingly, CA9 was upregulated in tumours, suggesting possible adaptation in vivo, consistent with its known roles in regulating pH during tumour adaptation to hypoxia and acidosis, facilitating metabolic reprogramming of cancer cells." (PMID 41226720, 2025). "In tumor cells, lactate promotes tumor cell invasion by up-regulating CA9 expression." (PMID 40165895, 2025). "CA9 was used as a marker for hypoxia-positive tumor regions." (PMID 41150697, 2025). "However, as compared to CA12, CA9 received more attention for targeted therapy due to its elevated expression in various aggressive tumours with poor clinical outcomes as well as its strong connection with hypoxic tumour microenvironment." (PMID 38530845, 2024). "Tumor cells can upregulate carbonic anhydrase 9 (CA IX) activity through HIF to neutralize lactate." (PMID 39434182, 2024). "Overall, our results demonstrate that lncRNA ZNF674-AS1, which significantly up-regulated in chemotherapy non-response NB patients, plays a crucial role in promoting NB tumor development and inhibiting cisplatin-induced tumor cell pyroptosis through up-regulating CA9 by binding IGF2BP3." (PMID 38177154, 2024). "The DNA vaccine was composed of plasmid DNA encoding G250 protein (also known as carbonic anhydrase-9 that is abundantly expressed on RCC tumor cells but not on the normal non-cancerous cells) fused with the major immune-dominant region of the HBcAg gene." (PMID 39872522, 2024). "Therefore, therapeutic strategies explored to target acidosis and hypoxia in cancer treatment include inhibiting key enzymes like CA9, targeting hypoxia-induced pathways, and exploring novel approaches such as bicarbonate treatment to decrease tumor acidity." (PMID 38672570, 2024). "Our results indicated predominant TGFBI expression in tumor cells positive for HIF1α and CA9." (PMID 39346536, 2024). "Finally, with respect to tumor hypoxia and angiogenic pathways, it is necessary to mention that hypoxia markers (HIF1α, carbonic anhydrase 9 (CAIX) and Glut1) are regulated by MET (hepatocyte growth factor receptor)." (PMID 38255995, 2024). "CA9 is considered a marker of hypoxia and is activated when hypoxia-inducible factor 1-alpha (HIF-1α) accumulates, and hypoxia has been reported to be associated with increased tumor cell viability and malignancy and to promote tumor cell growth." (PMID 39471162, 2024). "CA9 is a critical factor in tumorigenesis and has been identified as a potential therapeutic target for various cancers, including NB, due to its up-regulated expression in tumor tissues." (PMID 38177154, 2024). "We found significantly higher mRNA levels of EGLN3, HIF1A, GLUT1, VEGF, and CA9 (p = 0.021; p < 0.0001; p < 0.0001; p = 0.004, and p < 0.0001, respectively) genes in tumor tissues compared to normal ones and downregulation of the EGLN1 mRNA level in tumor tissues (p = 0.0013)." (PMID 38928200, 2024). "Previous studies have shown that tumor‐infiltrating immune cell‐associated long non‐coding RNA (lncRNAs) are also implicated in cancer immunity regulation and the lncRNA IGFL2‐AS1 can mediate the inhibition of HIF‐1α degradation thus increase CA9 expression." (PMID 37194413, 2023). "Moreover, the combined treatment with cisplatin and CA9 inhibitor U104 was much more effective than cisplatin alone in the xenograft model containing heterogeneous tumor cell populations." (PMID 36760347, 2023).
tumor (continued). "Evidence also suggests that combinatorial targeting of CA9 with chemotherapy in chemoresistant tumours may re-sensitize tumour cells to anti-cancer therapy, in part by enhancing ferroptosis." (PMID 38099193, 2023). "Notably, CA9 inhibitor enhances the ferroptosis-inducing effect of cisplatin on gefitinib-resistant cells, thus eliminating resistant cells in heterogeneous tumor tissues." (PMID 36760347, 2023). "The regulatory effect of CA9 on the acid–base balance of the tumor microenvironment may be the key to its tumor‐promoting effect under the influence of IGFL2‐AS1 in CRC." (PMID 36537608, 2023). "However, following bevacizumab treatment CA9 expression decreased in BRAFWT tumor tissues and increased in BRAFV600E xenografts." (PMID 36539575, 2023). "In addition, IHC staining was performed to evaluate the protein expression of CA9 in CRC tissues and non‐tumor tissues, and the results showed that CA9 was upregulated in tumor tissues." (PMID 36537608, 2023). "In addition, western blotting and IHC staining were utilized to detect the protein levels of HIF‐1α and CA9 in tumor tissues from the nude mice in each group." (PMID 36537608, 2023). "We believe that CA9-BPS-Cu(ii) may have a role to play in controlling tumour regrowth and cancer metastasis and could prove particularly effective in targeting and eradicating CSCs." (PMID 36819853, 2023). "Notably, CA9 is a typical protein that can catalyze carbon dioxide to synthesize bicarbonate and proton in cells, which allows tumor cells to maintain a neutral pH even in the acidified microenvironment." (PMID 37194413, 2023). "This “oxygenation heterogeneity” was later confirmed by studies using chemical oxygen probes and the detection of transcripts or proteins induced by hypoxia at the particular tumour areas (e.g., CA9, VEGF, ANGPT2, EPAS1), with the rest of the tumour being relatively well-oxygenated." (PMID 36230775, 2022). "In order to investigate regions of hypoxia in the tumor section, CA-9 labeling wasperformed." (PMID 36412102, 2022). "A statistically higher CA9 expression in the Highplus subgroup can also be attributed to an acidic extracellular milieu, which might contribute to poor tumor differentiation and development as well as increased tumor growth." (PMID 36428766, 2022). "In addition, studies have also shown that carbonic anhydrase 9 (CA9) in exosomes released from hypoxic ccRCC cells can enhance angiogenesis in the tumor microenvironment, thereby promoting cancer progression." (PMID 36620603, 2022). "The CA9 is an endogenous marker for malignancy hypoxia, which regulates cellular PH in a hypoxic microenvironment and stimulates tumour cell proliferation by enhancing tumour acidosis." (PMID 36415514, 2022). "CA9 expression while highly upregulated in solid tumors, is also present minimally in normal tissues which may pose on-target, off-tumor toxicity challenges." (PMID 35874663, 2022). "The decrease in blood flow was consistent with CD31immunohistochemical analysis, where a significant reduction in tumor vascularizationwas observed.The decreases in tumor vascularization and blood flow observed here were accompaniedby an increase in CA-9 labeling compared to the untreated control." (PMID 36412102, 2022). "In CRC cell lines, CA9 promotes tumor growth and necrosis in vivo." (PMID 35440019, 2022). "CA9 equilibrates among hypoxia, iron metabolism, and redox regulation in tumor cells." (PMID 35626004, 2022). "However, on-target-off-tumor toxicity appears to be less of a concern in antibody mediated therapy as monoclonal antibody targeting of CA9 has been used for imaging and radio-immunotherapy without significant GI toxicity issues." (PMID 35874663, 2022). "The GLUT3 staining we observed in tumor tissue showed discrete patterns and gradients, concentrated with pimonidazole, and covered the greatest area within tumors as compared to the hypoxia markers CA9 and GLUT1." (PMID 35328229, 2022).